MTOR (mechanistic target of rapamycin kinase)
Diseases named in the same sentence as MTOR in open-access papers (continued):
Sharing a sentence is not in itself a finding about the gene and the disease.
Obesity (continued). "Adult mTOR-KOPlacenta offspring, under a metabolic high-fat challenge, displayed exacerbated obesity and metabolic dysfunction compared with littermate controls." (PMID 34032632, 2021). "The role of the mTOR signaling pathway in obesity and energy metabolism has been thoroughly investigated in the last two decades." (PMID 34099716, 2021). "As a critical regulator of metabolic syndrome, the mTOR pathway underwrites many diseases of overeating, including obesity and type 2 diabetes." (PMID 33947426, 2021). "A growing body of evidence shows that the mTOR pathway is strongly involved in initiating and developing obesity and insulin resistance in metabolic syndrome." (PMID 35178356, 2021). "Taken together, alteration in AMPK, SIRT1, and mTOR activity occur in energy surplus states such as obesity and type 2 diabetes to compensate for mitochondrial dysfunction and metabolic disorders." (PMID 34987473, 2021). "We found higher expression levels of Ki67 and phosphorylated-S6 in the tumor of obese mice than in that of lean mice, indicating that obesity promotes tumor proliferation and activates the mTOR pathway in endometrial tumors." (PMID 33557912, 2021). "Previous reports showed that metabolic reprogramming of NK cells in obesity limits the antitumor responses through different mechanisms, mainly through PPARα/δ pathway and inhibition of mTOR-mediated glycolysis." (PMID 34212054, 2021). "Our data demonstrate direct evidence for placental mTOR signaling in the regulation of fetal growth and the programming of obesity and T2D." (PMID 34032632, 2021). "The previous investigation exhibits that AMPK deficiency promotes obesity triggered cardiac hypertrophy and impair contractile function perhaps due to the affiliation with AS160 and mTOR signaling." (PMID 33414718, 2020). "The ratio of Akt and mTOR phosphorylation was determined in order to clarify the relationships between the Akt/mTOR pathway and oxidative stress in the obesity mice model." (PMID 32630592, 2020). "Hypothalamic mTOR in Tsc1 knockout rats was activated; the appetite of rats increased and obesity occurred." (PMID 33532487, 2020). "The role of cytokines, mammalian target of rapamycin (mTOR), and altered natural killer cell polarization in the dangerous liaison between COVID-19 and obesity are discussed here." (PMID 32759719, 2020). "Intriguingly, mTOR is also one of the signal mediators of obesity related factors, such as leptin, adiponectin, and inflammatory cytokines, through the Akt/PI3K or AMPK pathways." (PMID 33304380, 2020). "The mTOR signaling pathway in the mouse hypothalamus with Tsc1 gene deletion is activated, and the food intake of mice is increased and obesity occurs." (PMID 33532487, 2020). "Obesity upregulates the chronic hyperactivation of mTOR activity in multiple tissues, and increases S6K activity and over phosphorylation of translation suppressor 4E-BP." (PMID 32759719, 2020). "The expression of Tsc1 in DIO rats is downregulated, the mTOR signal in the hypothalamus is activated, and obesity in rats occurred, while DIO rats, on the contrary, showed obesity resistance." (PMID 33532487, 2020). "Suppression of mTOR signaling is thought to mediate major beneficial effects of caloric restriction including suppression of obesity, type 2 diabetes, cancer, and neurodegeneration." (PMID 32516922, 2020). "Res induced brown-like adipocyte phenotype in 3T3-L1 adipocytes partly via mTOR pathway, which provided new insights into the utilization of Res to prevent obesity and related comorbidities." (PMID 32047421, 2020). "In this regard, we recently reported that HFD-induced obesity in gerbils increased pro-inflammatory cytokines and mTOR activation, and elicited neuronal death in the striatum after TFI." (PMID 32832423, 2020).
Obesity (continued). "Future research efforts should use in-vitro and in-vivo approaches to understand the impact of the upregulation of inflammatory and mitogenic pathways, such as mTOR, in obesity on leukemia genesis and propagation." (PMID 33105727, 2020). "The gastrointestinal tract and gastrokines, together with novel systems such as the endocannabinoid system and the intracellular mTOR pathway, represent promising pharmacological targets for the development of therapies against obesity." (PMID 32784967, 2020). "In summary, FTO can directly or indirectly target mTOR, thus regulating the occurrence and progress of obesity and cancer in a broad manner." (PMID 33304380, 2020). "The diverse functionality of mTOR provides a very attractive drug target where dysfunctional mTOR signalling can lead to diseases such as cancer, type II diabetes, obesity, aging and neurodegenerative conditions." (PMID 33142217, 2020). "Our results provide the first evidence that LEP with anti-hepatic steatosis effects inhibits the ER stress-mediated autophagy in HFD-induced obesity models through the regulation of the PI3K/AKT/mTOR pathway." (PMID 32521713, 2020). "Altogether, these data provide a solid link between the miRNAs, obesity and endothelial dysfunction through mTOR regulation." (PMID 32907629, 2020). "As for FTO, it can participate in the disease progression of obesity and cancer in m6A-dependent post-transcriptional regulation, or by targeting mTOR." (PMID 33304380, 2020). "The objective of this study was to investigate the effects of obesity on tGCI-induced neuronal damage and inflammation in the striatum and to examine the role of mTOR which is involved in the pathogenesis of metabolic and neurological diseases." (PMID 30890150, 2019). "Conversely, pharmacological blockade of the mTOR pathway has been reported to reverse these obesity-induced effects in a model of Wnt1-induced primary mammary tumorigenesis." (PMID 30867005, 2019). "For example, one study showing apparently normal basal mTOR phosphorylation in those with obesity, did show increased phosphorylation of mTOR during the postprandial period." (PMID 31263701, 2019). "Accumulating evidence has shown that an abnormal mTOR signaling pathway plays a role in metabolic and neurological disorders, including obesity and brain ischemia." (PMID 31546722, 2019). "Activated mTORC1 signaling, as found in MSC in transition to calcifying osteoblasts, is the signature status of the mTOR network in conditions with prominent cardiovascular pathologies such as chronic nutrient overload, obesity, and diabetes mellitus type 221." (PMID 31882658, 2019). "RNA-sequencing of adipose tissue macrophages demonstrated a role for miR-146a in regulating both inflammation and cellular metabolism, including the mTOR pathway, during obesity." (PMID 30768595, 2019). "Genes from these enriched gene sets indicate a novel role for miR-146a in regulating the mTOR/AKT pathway which has previously been linked to cellular metabolism and obesity." (PMID 30768595, 2019). "Genetic activation of mTOR results in enhanced beta cell growth and increased insulin secretion in mouse beta cells, whereas pharmacological inhibition of mTOR dramatically inhibited insulin secretion and reduced beta cell mass in a rodent model of obesity." (PMID 30334081, 2019). "The phosphatidylinositol 3-kinase (PI3K)/V-Akt murine thymoma viral oncogene homolog (Akt) (PKB)/mechanistic target of rapamycin (mTOR) cascade is a key signaling pathway linking obesity and cancer and regulates cell proliferation, apoptosis, and metabolism." (PMID 29367689, 2018). "Tsc1 deletion mice developed hyperphagia, increased fat pads, and obesity and displayed increased activity of mTOR signaling." (PMID 29853949, 2018).
Obesity (continued). "Other studies have demonstrated increased mTOR/S6K1 activation in the transgenic Zucker obese (ZO) rat, a model of overnutrition and obesity which carries a mutation of the leptin receptor and develops INS resistance and glucose intolerance." (PMID 30116740, 2018). "ILK is connected with numerous intracellular signalling pathways, such as the mammalian target of rapamycin (mTOR), a serine-threonine kinase, which plays an essential role in autoimmune disorders, obesity and aging." (PMID 30271655, 2018). "We have previously shown that Sam68-deficient mice have a lean phenotype and are protected against dietary-induced obesity due to defects in mTOR and S6K1 alternative splicing." (PMID 29137239, 2017). "It has been previously demonstrated that in rodents HFD-induced obesity increases activation of mTOR pathway in liver and skeletal muscle." (PMID 28325885, 2017). "Deletion of Raptor, a component of mTOR C1, specifically in the adipose tissue protected against diet-induced obesity, whereas deletion of Raptor in skeletal muscle was deleterious, causing severe muscular dystrophy." (PMID 28795262, 2017). "In obesity, the mTOR pathway is hyper-activated in the adipose tissue thus leading to increased lipogenesis, reduced lipolysis and fat accumulation." (PMID 28795262, 2017). "The published data indicated that AKT/mTOR deregulation occurs in human metabolic diseases, such as type 2 diabetes or obesity." (PMID 28972559, 2017). "Similarly, disturbed autophagy also plays a pivotal role in the pathogenesis of cardiomyopathy associated with uncorrected obesity named cardiomyopathy of obesity, and suppression of mTOR may act as a possible approach to hinder pathological cardiac hypertrophy by saving interrupted autophagic flux." (PMID 28691015, 2017). "Akt-mTOR signaling is well-known as positive regulator of adipogenesis and inhibition of this pathway protects from obesity." (PMID 28316325, 2017). "It has been postulated that chronic diseases associated with aging, such as cancer or obesity, are driven by the overactivation of the nutrient-sensing mTOR gerogene due to the loss of responsiveness to active AMPK, a suppressor of mTOR." (PMID 28278224, 2017). "In obese mice, the expression of VEGF, IKKβ, and mTOR are up-regulated in tumors and the levels of various adipokines are modulated during the development of obesity, perhaps crucially contributing to breast carcinogenesis." (PMID 26794215, 2016). "Testing anti-obesity effects of pan-mTOR inhibitors will allow investigators to determine their effective doses and schedules within several months." (PMID 28077803, 2016). "We aimed to determine the effect of exercise and dietary change on biochemical changes of mTOR signaling pathway, in case of obesity induced by continuous consumption of high fat diet." (PMID 27508151, 2016). "Since mice that were chronically fed a HFD showed defects in autophagy, obese mice were treated with rapamycin, an mTOR inhibitor that induces autophagy, to determine if activation of hypothalamic autophagy reverses the deleterious effects of obesity." (PMID 25786112, 2015). "The mammalian target of rapamycin (mTOR) is at the crossroads of a nutrient-hormonal signaling network that is involved in specific pathological responses, including obesity." (PMID 24587943, 2014). "Calorie restriction (CR) is a well-known dietary regimen that prevents or reverses obesity and suppresses tumorigenesis in a variety of animal models, at least in part via inhibition of mammalian target of rapamycin (mTOR) signaling." (PMID 24685128, 2014). "Obesity also results in reduced insulin sensitivity and altered signal transduction pathways, such as P13Kinase and mammalian target of rapamycin (mTOR), and in mitochondrial metabolism." (PMID 25467785, 2014).
Obesity (continued). "Increased activation of mTOR is common in tumors and many normal tissues from obese and/or diabetic mice, and specific mTOR inhibitors block the tumor-enhancing effects of obesity in mouse models (15–, 17)." (PMID 23967401, 2013). "Experimentally altered gut microbiota in mice has led to obesity, metabolic syndrome and insulin resistance: disorders related to the insulin/mTOR signaling pathway." (PMID 23682635, 2013). "Dietary leucine has been shown to decrease diet-induced obesity and to activate the mammalian target of rapamycin (mTOR) signalling and to decrease food intake and body weight." (PMID 23505546, 2013). "In diet-induced obesity, overactivation of mTOR-S6K signaling favors expansion of the WAT mass, leading to insulin resistance of adipocytes through elevated serine phosphorylation of IRS1." (PMID 24391749, 2013). "Without discussing them again, I emphasize one universal mechanism that obesity promotes cancer by over-activating the nutrient-sensing mTOR pathway in both normal and cancer cells." (PMID 23565531, 2012). "Key among the signaling pathways linking obesity and cancer is the PI3K/Akt/mTOR cascade, which is a target of many of the obesity-associated factors and regulates cell proliferation and survival." (PMID 23050962, 2012). "Increased activation of mTOR is common in tumors and many normal tissues from obese and/or diabetic mice, and specific mTOR inhibitors block the tumor-enhancing effects of obesity in mouse models." (PMID 23050968, 2012). "C/EBPβ-LIP:LAP ratio is regulated by endoplasmic reticulum (ER) stress and mTOR signalling, both of which are altered in obesity." (PMID 22662254, 2012). "Our data also describe activation of hypothalamic mTOR signaling as a mediator of food intake, of potential importance for the understanding and treatment of obesity." (PMID 23056530, 2012). "Chronic hyperactivation of mTOR signaling is atypical outside of disease states, such as obesity, dyslipidemia, hypercholesterolemia, or certain types of cancer." (PMID 21386136, 2011). "Persistent activation of mTOR/S6K1 signalling has been shown to be associated with organism aging and aging-associated pathologies such as cancer, left ventricular hypertrophy, obesity, and muscle degeneration in animal models." (PMID 21544240, 2011). "First, it is not clear that the magnitude of increase in fasting blood BCAA in obesity or T2DM are of high enough magnitude to trigger mTOR to a level that would negatively impact insulin action in situ." (PMID 21170321, 2010). "By restoring mTOR regulation and promoting autophagy, anthocyanins could play a crucial role in reducing the pathological effects of obesity, including excessive fat accumulation and metabolic dysfunction." (PMID 40218884, 2025). "From a clinical standpoint, repurposing mTOR inhibitors for BMI reduction could provide a targeted strategy for obesity management, particularly in individuals with metabolic syndrome." (PMID 40299431, 2025). "mTOR signaling pathway coordinates the nutrient-mediated metabolism, immune responses, and cell-cycle progression, and dysregulation of mTOR could lead to various diseases such as cancer and obesity." (PMID 40388307, 2025). "Pathway and ontology analyses indicated that miR-15b, miR-26a, miR-301, miR-30b, and miR-30c participate in essential processes related to obesity, such as adipogenesis, fatty acid oxidation, mTOR (mechanistic target of rapamycin kinase) signaling, PPAR signaling, and Wnt signaling." (PMID 40149500, 2025). "The overactivation of mTOR is involved in the development of obesity and IR." (PMID 40149500, 2025). "Moreover, chronic mTOR activation in POMC neurons during aging can paradoxically lead to hyperphagic obesity, suggesting that the effect of mTOR depends on the dosage and duration of its activation." (PMID 41516046, 2025).
Obesity (continued). "Enhanced mTOR signaling is also associated with the overactivation and depletion of primordial follicles, suggesting that obesity may accelerate ovarian reserve depletion by excessively activating mTOR pathways." (PMID 41321496, 2025). "Additionally, the total protein levels of PI3K, AKT, and mTOR were unchanged by either overexpression or downregulation of these “pro-obesity” miRNAs." (PMID 40016734, 2025). "The findings reveal that pea fibre may prevent obesity through the SHMT2/glycine/mTOR/PPAR-γ signal pathway." (PMID 40075937, 2025). "The translation repressor 4E-BP1 is a known substrate of the mTOR (Mechanistic Target of Rapamycin) signaling pathway, which regulates important cellular processes and is involved in several pathological conditions, including type 2 diabetes, obesity and cancer." (PMID 39962379, 2025). "Further, mTOR is involved in inflammation control, and its activation within liver and fat tissue may enhance chronic low-grade inflammation, a feature of obesity." (PMID 40218884, 2025). "Growth and meat quality traits were evident through CAST (calpastatin, regulating muscle tenderness), FTO (fat mass and obesity‐associated gene, impacting fat deposition), GHR (growth hormone receptor) and MTOR (mechanistic target of rapamycin, controlling muscle protein synthesis)." (PMID 40859468, 2025). "Anthocyanins may help regulate mTOR activity, offering a potential mechanism for their anti-obesity effects." (PMID 40218884, 2025). "Furthermore, Roseburia hominis exerts its anti-obesity effects primarily through upregulation of the SIRT1/mTOR signaling pathway, as demonstrated by both its live bacteria and its culture medium." (PMID 41488302, 2025). "We have previously shown that DHA inhibits mTOR activity in trophoblast cells, which may indicate that DHA supplementation is a mechanism for reducing mTOR activity in the placentas of pregnancies complicated by obesity by lowering activating phospholipids." (PMID 39275250, 2024). "Moreover, in vitro studies have confirmed that adiponectin can inhibit tumor growth by activating AMP-activated protein kinase (AMPK) and inhibiting the mammalian rapamycin target (mTOR) pathway, validating the role of obesity in TFE3-RCC." (PMID 38261736, 2024). "mTOR signaling is overactivated in obesity, promoting inflammation and IR." (PMID 39728125, 2024). "In addition, obesity is linked to the activation of the PI3K/AKT pathway, including mechanistic target of rapamycin kinase (MTOR) and other downstream proteins." (PMID 39769193, 2024). "However, recently the dysregulation of mTOR has been related to several metabolic conditions, notably obesity and T2DM." (PMID 39261960, 2024). "However, there is still limited evidence regarding the effect of IF and aerobic exercise in reducing human mTOR levels, especially in obese females, through IF and aerobic exercise, and thus their potential to be used as a combined obesity treatment." (PMID 38786985, 2024). "It is known that excessive food intake and obesity activate mTOR through PI3K/Akt, IGF-1, and AMPK." (PMID 39339816, 2024). "In a pathological state, excessive energy intake may lead to metabolic disturbance and overactivation of mTOR, thus increasing adipogenesis and fat storage, which contribute to obesity." (PMID 38786985, 2024). "PEITC supplementation was able to decrease the expression levels of NF-κB, LOX-1, and COX-2, ameliorating obesity-induced inflammation via mTOR/PPARγ/AMPK signaling (mammalian target of rapamycin/peroxisome proliferator-activated receptor gamma/adenosine-monophosphate activated-protein kinase)." (PMID 38542669, 2024). "The cAMP signaling pathway and mTOR signaling pathway are relatively pervasive second messengers that are significantly altered after bariatric surgery, and they are involved in many molecular pathways in obesity and metabolic diseases." (PMID 39010180, 2024).